ZNF280B (zinc finger protein 280B)
Description:
May function as a transcription factor.
Synonyms: SUHW2; ZNF279; ZNF632; 5'OY11.1; D87009.C22.3
Tractability: PROTAC: UniProt records ubiquitination sites on it.
Gene: Protein-coding gene on chromosome 22 (22,484,421 to 22,508,742, reverse strand). Ensembl gene ENSG00000275004.
Subcellular location: Nucleus
Subcellular location (Human Protein Atlas): Nucleoplasm
Gene Ontology:
Molecular function: DNA-binding transcription factor activity, RNA polymerase II-specific; RNA polymerase II cis-regulatory region sequence-specific DNA binding
Biological process: regulation of DNA-templated transcription; regulation of transcription by RNA polymerase II
Cellular component: nucleus
Genetic constraint (gnomAD): Loss-of-function variants: 16 observed, 39.64 expected, observed/expected ratio (o/e) 0.4, 90% interval 0.27 to 0.61. The upper end of that interval is the gene's LOEUF score, 0.61, which puts it in group 2 of 6, group 1 being the genes least tolerant of losing a copy. Missense variants: 581 observed, 668.14 expected, observed/expected ratio (o/e) 0.87, 90% interval 0.81 to 0.93. Synonymous variants: 253 observed, 241.42 expected, observed/expected ratio (o/e) 1.05, 90% interval 0.94 to 1.16.
Homologues: Orthologues: chimpanzee ZNF280B (99% identical), macaque ZNF280B (95% identical), dog ZNF280B (81% identical), rabbit ZNF280B (77% identical), pig ZNF280B (76% identical), guinea pig ZNF280B (74% identical), mouse Zfp280b (66% identical), rat Zfp280b (64% identical). Paralogues in human: ZNF280A (63% identical), ZNF280D (53% identical), ZNF280C (46% identical), ZBTB49 (15% identical), GFI1 (13% identical), BCL6 (13% identical), FEZF2 (12% identical), ZBTB21 (12% identical), FEZF1 (12% identical), PRDM13 (11% identical), ZBTB14 (10% identical), GFI1B (10% identical), and 16 more.
Diseases named in the same sentence as ZNF280B in open-access papers:
ZNF280B is named in the same sentence as 8 diseases in open-access papers, as found by Europe PMC text mining. Sharing a sentence is not in itself a finding about the gene and the disease. The quoted sentences say what the papers report.
prostate carcinoma (4 papers, 2014 to 2022). A carcinoma that arises from epithelial cells of the prostate gland. "The knockdown and overexpression of ZNF280B protein have demonstrated that ZNF280B is involved in both pro-growth and pro-survival functions in prostate cancer." (PMID 25319049, 2014). "ZNF280B is an oncogene in the prostate cancer and gastric cancer." (PMID 35484552, 2022).
breast tumors (1 paper, 2018). "Using data available from The Cancer Genome Atlas (TCGA), we correlated expression of four genes (MKRN3, TPPA, ZNF280B, and XKR6) with DNA methylation in 553 breast tumors." (PMID 30352973, 2018).
metabolic syndrome (1 paper, 2022). A cluster of metabolic risk factors for CARDIOVASCULAR DISEASES and TYPE 2 DIABETES MELLITUS. "Our study is the first to point out that ZNF280B mutation is related to metabolic syndrome." (PMID 35484552, 2022).
ZNF280B also shares sentences with these, for which no sentence is quoted: tumor (2 papers); cancer (1); gastric cancer (1); goblet cell adenocarcinomas (1); pancreatic cancer (1).